MIR4654 (microRNA 4654)
Synonyms: hsa-mir-4654; mir-4654
Gene: MicroRNA gene on chromosome 1 (162,157,107 to 162,157,182, forward strand). Ensembl gene ENSG00000266144.
Homologues: Orthologues: chimpanzee MIR4654 (100% identical).